LCAT (lecithin-cholesterol acyltransferase)
Diseases named in the same sentence as LCAT in open-access papers (continued):
Sharing a sentence is not in itself a finding about the gene and the disease.
Norum disease (3 papers, 2022 to 2025). A form of lecithin-cholesterol acyltransferase deficiency (LCAT) characterized clinically by corneal opacities, hemolytic anemia, and renal failure, and biochemically by severely decreased HDL cholesterol and complete deficiency of the LCAT enzyme. "In Norum disease both activities (alpha and beta) of the LCAT enzyme are lost causing very low levels of HDL-C (below the 5th percentile), increased TG and decreased LDL-C." (PMID 35743896, 2022).
schistosomiasis (3 papers, 2014 to 2025). An infectious disease caused by parasitic trematodes of the genus Schistosoma that colonize human blood vessels and release eggs that can cause granulomatous reactions leading to acute (swimmer's itch or acute schistosomiasis syndrome) or chronic disease. "For example, we have reported LCAT deficiency in human and animal schistosomiasis, while decreased CETP activity is a feature of the acute-phase response and raises HDL levels, particularly ApoE-rich HDL." (PMID 25051269, 2014). "ApoA1 interacts with LCAT, influencing lipid metabolism and immune responses during infection; thereby suggesting a complex interplay between lipoproteins and immune modulation in schistosomiasis." (PMID 40853910, 2025).
alcoholic hepatitis (2 papers, 2020 to 2022). Acute hepatitis resulting from ingestion of alcohol. "In both cases of obstructive jaundice and alcoholic hepatitis, it has been suggested that functional deficiency of LCAT could be responsible for the altered lipid composition in LP-Z." (PMID 32927635, 2020). "What remains unclear is how LCAT becomes deficient in both obstructive jaundice and alcoholic hepatitis." (PMID 32927635, 2020). "Very recently, it was suggested that compromised LCAT and HL activities may at least in part be responsible for the high prevalence of plasma LP-Z in alcoholic hepatitis." (PMID 35268313, 2022).
Alzheimer’s disease dementia (2 papers, 2022 to 2023). "HDL LCAT activity and particle size were positively correlated with the neuropsychological scores and negatively correlated with the clinical dementia rating." (PMID 35884800, 2022). "We also observed that individuals with APOE3/E4 genotype had lower CEC and LCAT activity than individuals with APOE3/E3 genotype regardless of dementia diagnosis [143•]." (PMID 37702886, 2023).
amyloidosis (2 papers, 2012 to 2020). A disorder characterized by the localized or diffuse accumulation of amyloid protein in various anatomic sites. "These ApoA1 variants have undeniable interest because they may affect lecithin-cholesterol acyltransferase (LCAT) activity and promote the formation of amyloidosis." (PMID 32456156, 2020). "L144R is unable to activate LCAT, while S36A, F71Y, K107del, have been associated with amyloidosis." (PMID 23209431, 2012).
chronic kidney failure (2 papers, 2021). "Animal studies have firstly shown that chronic kidney failure is associated with hepatic downregulation of the LCAT gene, which leads to an impaired LCAT activity." (PMID 33807271, 2021). "In addition, HDL abnormalities associated to chronic kidney failure (CKF) are largely due to marked downregulation of LCAT activity." (PMID 34548543, 2021).
Corneal opacity (2 papers, 2019 to 2024). A reduction of corneal clarity. "LCAT enzyme therapy might prevent serious complications, particularly renal dysfunction and corneal opacity." (PMID 39204178, 2024). "Additionally, LCAT deficiency often leads to reduced plasma HDL-c, corneal opacity, anemia, and renal issues." (PMID 39204178, 2024).
depression (2 papers, 2024 to 2025). "Overall, HDL-C reduction in depression reflects a multifactorial pathology involving LCAT/apoA1/PON1 dysfunction, cortisol-driven lipid dysregulation, and pro-inflammatory HDL remodeling." (PMID 40511456, 2025).
Hypocholesterolemia (2 papers, 2011 to 2017). An decreased concentration of cholesterol in the blood. "The aqueous extract of C. occidentalis has an hypocholesterolemia effect and could then act effectively against the transport of cholesterol by the increase in the activity of the LCAT, thus resulting in enrichment of the HDL-c out of cholesterol esters." (PMID 28122565, 2017). "It has been postulated hypocholesterolemia in sickle cell patients is due to haemodilution, down regulation of cholesterol synthesis, and decreased transfer of cholesterol from membrane to circulating high-density lipoprotein (HDL) because of reduced activity of lecithin-cholesterol acyltransferase." (PMID 21941660, 2011).
hypothyroidism (2 papers, 2019 to 2022). Abnormally low levels of thyroid hormone. "Decreased lecithin–cholesterol acyltransferase (LCAT) activity can occur in rats with induced hypothyroidism." (PMID 35448493, 2022). "Namely, studies involving human subjects and animal models have demonstrated that hypothyroidism is associated with decreased activities of cholesteryl-ester transfer protein (CETP), lecithin:cholesterol acyltransferase (LCAT), and HL." (PMID 31920978, 2019).
liver failure (2 papers, 2021 to 2024). A liver disease characterized by the liver losing or has lost all of its function. "Other important disease-relevant processes such as liver failure (LCAT, LDHA), complement activation (C3) and tissue damage (MB, H2AC17, ACTB) were also represented by the ML features." (PMID 39681038, 2024).
lung carcinoma (2 papers, 2021 to 2023). "However, there has been limited study of LCAT in lung and lung cancer cells." (PMID 36903601, 2023). "In this study, we found that METTL3 is up-regulated in lung cancer, and overexpressed METTL3 mediates m6A modification of LCAT, leading to its stabilization, thus providing molecular insight for LCAT3 overexpression in LUAD." (PMID 34274028, 2021).
osteoporosis (2 papers, 2019 to 2022). A condition of reduced bone mass, with decreased cortical thickness and a decrease in the number and size of the trabeculae of cancellous bone (but normal chemical composition), resulting in increased fracture incidence. "Low LCAT level was also associated with low bone mineral density (BMD) and osteoporosis." (PMID 36588724, 2022).
psoriasis (2 papers, 2020 to 2025). An autoimmune condition characterized by red, well-delineated plaques with silvery scales that are usually on the extensor surfaces and scalp. "Plasma in psoriasis patients has been shown to have reduced activity of haptoglobin, an acute phase glycoprotein, and an LCAT inhibitor." (PMID 32916896, 2020).
rheumatoid arthritis (2 papers, 2013 to 2022). A chronic, systemic autoimmune disorder characterized by inflammation in the synovial membranes and articular surfaces. "Moreover, LCAT activity was also decreased in patients with Rheumatoid arthritis and Systemic lupus erythematosus." (PMID 36588724, 2022).
Schnyder corneal dystrophy (2 papers, 2019 to 2021). Schnyder corneal dystrophy (SCD) is a rare form of stromal corneal dystrophy characterized by corneal clouding or crystals within the corneal stroma, and a progressive decrease in visual acuity. "In the case of LCAT deficiency and Schnyder corneal dystrophy, histochemical and chemical analysis including that presented here show the presence of cholesterol and phospholipid as a component of the extracellular lipid deposits." (PMID 31779197, 2019). "Ultrastructurally, the lipid in Schnyder corneal dystrophy (defective UBIAD1) also accumulates as extracellular membranous and vacuolar structures like that seen in LCAT deficiency, but additionally within cholesterol crystals in about half the cases." (PMID 31779197, 2019).
thyroid cancer (2 papers, 2025). "Plasma proteomic studies have found that LCAT, GPX3, and leukotriene b4 can serve as potential biomarkers for thyroid cancer, and serum ISG15 and PLXNB2 can also serve as potential biomarkers." (PMID 40265010, 2025).
type 1 diabetes (2 papers, 2013 to 2023). "In our study, LPC was associated negatively to BMI and waist circumference, possibly reflecting altered LCAT activity or LPC catabolism in patients with type 1 diabetes and normal weight status." (PMID 37237999, 2023). "Our observation confirms previous studies on humans which report no significant change in LCAT levels in type 1 diabetes." (PMID 23691522, 2013).
Acute hepatitis (1 paper, 2022). Acute hepatic injury resulting from inflammation typically accompanied by increased serum alanine transaminase activity. "Cholesterol-esterifying activity in serum was found to be decreased in patients with acute hepatitis and chronic alcoholic liver disease, and besides LCAT, CE hydrolase seems to have a function herein." (PMID 36551908, 2022).
angina (1 paper, 2025). "FFDS has demonstrated its potential in reducing circulating TG levels and angina frequency in patients with SCHD, which may be due to the active ingredients of FFDS acting on LPL, CD36, FABPpm, L-FABP, LCAT, and CEPT." (PMID 39944604, 2025).
arteriosclerosis (1 paper, 2018). A vascular disorder characterized by thickening and hardening of the walls of the arteries. "Likewise, increased levels of lecithin-cholesterol acyltransferase activity have been reported as an RCT-activating factor under the circumstances of progressing arteriosclerosis in the presence of lipid metabolism abnormality." (PMID 29159568, 2018).
Astigmatism (1 paper, 2025). A type of refraction error associated with abnormal curvatures on the anterior and/or posterior surface of the cornea. "Accordingly, the aim of the present study was to compare best-corrected visual acuity (BCVA), corneal astigmatism, forward light scattering, and contrast sensitivity between patients with LCAT abnormalities - namely, FED and LCAT deficiency - and healthy controls." (PMID 41542003, 2025).
bone tumor (1 paper, 2025). "Immunofluorescence experiments showed that LCAT is located in the nuclei of cervical cancer cell line A431 and glioblastoma cell line U-251 MG and is almost not expressed in malignant bone tumor cell line U20S." (PMID 40003919, 2025).
central obesity (1 paper, 2022). "Overall, our results suggest that central obesity and MetS are associated with an impairment of HDL phospholipid metabolism and composition, which is partially driven by the lower activity of LCAT, with major changes correlating with the metabolic impairment of the patients." (PMID 35743227, 2022).
cognitive decline (1 paper, 2023). "Taken together, the reported results suggest that LCAT-mediated cholesterol esterification could represent a potential target of novel therapeutic interventions in AD, although the causality between esterification abnormalities and related cognitive decline cannot be established from our data." (PMID 37210544, 2023).
colon adenocarcinoma (1 paper, 2025). "Conversely, in adrenocortical carcinoma (ACC) and colon adenocarcinoma (COAD), high LCAT expression correlates with worse outcomes, indicating a potential oncogenic role." (PMID 40003919, 2025).
Corneal astigmatism (1 paper, 2025). "Our results indicated that, although BCVA and corneal astigmatism were comparable to those of age- and sex-matched controls, forward scattering was considerably increased, and contrast sensitivity was markedly decreased in patients with LCAT abnormalities." (PMID 41542003, 2025).
coronary artery calcification (1 paper, 2021). Calcification of the coronary artery, used as a measure of coronary atherosclerosis, a risk factor for myocardial infarction. "In our previous study, we found that LCAT in HDL is negatively and significantly associated with coronary artery calcification in the model adjusted for multiple clinically relevant covariates, but the association loses significance when the model was further adjusted for lipid levels." (PMID 34634315, 2021).
cyst (1 paper, 2022). A sac-like closed membranous structure that may be empty or contain fluid or amorphous material. "It is suggested that the decreased expression and/or activity of lecithin cholesterol acyltransferase in the cyst fluid leads to the accumulation of unesterified cholesterol, which is associated with the formation of cholesterol granuloma in the cyst wall." (PMID 36160115, 2022).
diabetic nephropathy (1 paper, 2025). "CE induces renal cell damage by increasing LCAT and ACAT levels and decreasing ABCA1 levels when diabetic nephropathy (DN) is fed a high-fat diet, leading to abnormal lipid metabolism." (PMID 40268915, 2025).
endotoxemia (1 paper, 2021). "During endotoxemia, HDL particle remodeling is associated with increased endothelial lipases and sPLA2 and decreased plasma cholesteryl ester transfer protein (CETP) and lecithin-cholesterol acyltransferase activity." (PMID 34087197, 2021).
gastric cancer (1 paper, 2016). A primary or metastatic malignant neoplasm involving the stomach. "There are few studies on LCAT and SRPX in cancer metastasis, with only one reported that SRPX is upregulated in gastric cancer cells after depletion of TWIST, which promoted the epithelial-mesenchymal transition that occurs during the initial steps of tumour metastasis." (PMID 27567667, 2016).
glioma (1 paper, 2025). A benign or malignant brain and spinal cord tumor that arises from glial cells (astrocytes, oligodendrocytes, ependymal cells). "Further analysis of LCAT expression in multiple tumors from the TCGA database found that LCAT expression is highest in Brain Lower Grade Glioma tissue." (PMID 40003919, 2025).
heart failure (1 paper, 2024). Inability of the heart to pump blood at an adequate rate to meet tissue metabolic requirements. "Although our observational design prevents definitive causal claims, these findings strongly suggest that LCAT activators merit exploration as potential therapeutic targets for heart failure in patients with CKD." (PMID 39154733, 2024). "Given the current lack of therapies proven to reduce morbidity and mortality in patients with heart failure and CKD, our results support the hypothesis that pharmacological modulation of LCAT strengthens the case for potential treatment for ADHF in patients with CKD." (PMID 39154733, 2024).
Hepatitis (1 paper, 2020). Inflammation of the liver. "Additionally, d-Gal/LPS could induce hepatitis in experimental rats, and lycopene significantly reduced the lipid metabolizing enzymatic activity (i.e., LPL, lecithin-cholesterol acyltransferase (LCAT), hepatic triglyceride lipase (HTGL), and increase in the HDL level)." (PMID 32759751, 2020).
hereditary amyloidosis (1 paper, 2012). Hereditary amyloidosis refers to a group of inherited conditions that make up one of the subtypes of amyloidosis. "This becomes especially important, if the gene under study has pleiotropic effects, i.e. affects multiple phenotypic traits, as is the case for APOA1: mutations in APOA1 have been associated with an inability to activate LCAT and with hereditary amyloidosis." (PMID 23209431, 2012).
hyperalphalipoproteinemia (1 paper, 2020). An autosomal dominant genetic condition caused by mutation(s) in the CETP gene, encoding cholesteryl ester transfer protein. "A decrease in the content of LCAT and SCARB1 transcripts may be suggested to result in the diminished flow of cholesteryl ester to the liver, thus contributing to hyperalphalipoproteinemia." (PMID 33269026, 2020).
hyperlipemia (1 paper, 2019). "In particular, induction of hyperlipemia in rats fed a hyperlipemic rich diet for 90 consecutive days was accompanied by a significant increase of ACAT and CETP, this effect being associated with a significant reduction of LCAT and PON1 compared to normolipemic animals." (PMID 31101130, 2019). "The effect of BPF in counteracting alteration of the lipemic serum and glycemic profile induced by diet-related hyperlipemia was accompanied by significant improvement of Lipid Transport Protein System as detected by measurements of ACAT, LCAT, CETP and PON1." (PMID 31101130, 2019).
injury (1 paper, 2022). Damage inflicted on the body as the direct or indirect result of an external force, with or without disruption of structural continuity. "Loss of LCAT could lead to serious lipid profile change and thus caused serious concurrent diseases like kidney injury." (PMID 36588724, 2022).
Kearns-Sayre syndrome (1 paper, 2016). Kearns-Sayre syndrome (KSS) is a mitochondrial disease characterized by progressive external ophthalmoplegia (PEO), pigmentary retinitis and an onset before the age of 20 years. "The primary diagnosis of one of these two patients was lecithin-cholesterol acyltransferase (LCAT) deficiency and that of the other patient was Kearns-Sayre syndrome (KSS)." (PMID 27086477, 2016).
leptospirosis (1 paper, 2020). A contagious bacterial infection caused by spirochetes of the genus Leptospira. "Our study showed a reduction of LCAT activity that reflected ina decrease of EC levels in patients with leptospirosis, resulting in an increase inFC." (PMID 32578717, 2020). "Weobserved a fractional LCAT activity reduction in patients with leptospirosis.Cisternas and Milstein-Kuschnaroff alsoreported a reduction in fractional LCAT rate in patients with leptospirosis inrelation to the control." (PMID 32578717, 2020).
liver dysfunction (1 paper, 2020). "Other blood parameters and markers of liver dysfunction such as aspartate aminotransferase, alanine aminotransferase, apolipoprotein B and lecithin cholesterol acyltransferase (LCAT) were not impacted." (PMID 33019707, 2020).
low grade glioma (1 paper, 2025). A grade I or grade II glioma arising from the central nervous system. "In low-grade glioma (LGG) and liver hepatocellular carcinoma (LIHC), low LCAT expression is associated with poor prognosis, suggesting a tumor-suppressive function." (PMID 40003919, 2025).
malaria (1 paper, 2023). Malaria is a serious and sometimes fatal disease caused by a parasite that commonly infects a certain type of mosquito which feeds on humans. "However, a lecithin:cholesterol acyltransferase (LCAT) previously implicated in liver stage merozoite egress in the rodent malaria parasite P. berghei, was detected in all the samples indicating that this enzyme is constitutively resident in the PV." (PMID 37352369, 2023). "We thus show that, in addition to its previously demonstrated role in liver stage merozoite egress, LCAT is required to facilitate efficient egress in asexual blood stage malaria parasites." (PMID 37352369, 2023).
mesothelioma (1 paper, 2025). A usually malignant and aggressive neoplasm of the mesothelium which is often associated with exposure to asbestos. "In ACC, COAD, kidney renal clear cell carcinoma (KIRC), and mesothelioma (MESO) patients, high LCAT expression is associated with poor OS prognosis." (PMID 40003919, 2025).
metastatic tumour (1 paper, 2016). "Six genes were associated with tumour pathologic PT and tumour stage; among these, high expression of INTS8 and UBAP2L, and low expression of ACSM3, FCN2, LCAT, and MT1G, was significantly associated with metastatic tumour and late stage (P ≤ 0.05)." (PMID 27567667, 2016).
pancreatic adenocarcinoma (1 paper, 2025). "Our analysis of LCAT methylation level differences in different tumors found that compared to normal tissues, LCAT is hypermethylated in BRCA, COAD, HNSC, LUSC, PRAD, and UCEC and hypomethylated in KIRC, KIRP, and pancreatic adenocarcinoma (PAAD)." (PMID 40003919, 2025).
parasitemia (1 paper, 2024). "The importance of LCAT in Plasmodium replication is demonstrated by mutant studies that showed parasites lacking LCAT clump together and are also unable to escape infected RBCs resulting in a reduction in the rate of parasitemia." (PMID 38455763, 2024).
periodontitis (1 paper, 2019). An acute or chronic inflammatory process that affects the tissues that surround and support the teeth. "Furthermore, higher LCAT and cholesteryl ester transfer protein activities after periodontal treatment support the hypothesis of reduced activation of these proteins and reversed cholesterol transport during periodontitis." (PMID 30842338, 2019).